RET (ret proto-oncogene)
Diseases named in the same sentence as RET in open-access papers (continued):
Sharing a sentence is not in itself a finding about the gene and the disease.
medullary thyroid carcinoma (continued). "Overall, our data reveal that CDK5 activation occurs after RET activation by GDNF stimulation, suggesting that CDK5 may be a potential downstream of RET protein in GDNF-induced human medullary thyroid cancer cell proliferation." (PMID 34207842, 2021). "Point mutations represent the main RET alteration in medullary thyroid cancer and may occur in either the extracellular domain or the intracellular TKI domain, resulting in a ligand-independent RET activation." (PMID 34503226, 2021). "Medullary thyroid carcinoma occurs in 25% of the dominant component of hereditary multiple endocrine neoplasia type 2 (MEN2); mutations of the proto-oncogene RET are the most frequently involved in cancer pathogenesis, but there are many other mutation patterns." (PMID 34640473, 2021). "MEN2B is caused by mutations in the RET gene, and is associated with medullary thyroid carcinoma, pheochromocytoma, marfanoid habitus, and multiple mucosal neuromas involving the face, as compared to CS, which presents with multiple neuromas affecting acral sites." (PMID 34179044, 2021). "Interestingly, we identified for the first time that CDK5 physically interacts with RET protein in GDNF-induced medullary thyroid cancer cell proliferation." (PMID 34207842, 2021). "Although medullary thyroid cancer development was associated with mutations of RET tyrosine kinase, no information is available about a possible interaction between HIV and thyroid tissue, as described for EBV45." (PMID 31857648, 2019). "Somatic point mutations in RET are associated with familiar or sporadic medullary thyroid cancer, since RET is normally expressed in C cells, but not in follicular thyroid cells." (PMID 29629339, 2018). "The RET level was decreased in a medullary thyroid cancer cell line." (PMID 28476040, 2017). "Vandetanib and cabozantinib, both multi-kinase inhibitors with RET activity, are approved for use in medullary thyroid carcinoma, but additional pharmacological activities, most notably inhibition of vascular endothelial growth factor - VEGFR2 (KDR), lead to dose-limiting toxicity." (PMID 27429741, 2016). "Indeed, targeting the RET tyrosine kinase activity is already an active line of research for the development of therapies against other RET-related tumors such as Medullary Thyroid Carcinoma." (PMID 27034161, 2016). "The RET status was found to correlate with the outcome of sporadic medullary thyroid carcinoma." (PMID 27092013, 2016). "Medullary thyroid cancer (MTC) accounts for 3–10% of all thyroid malignancies and can be classed as “sporadic” (SMTC; 75%) or “hereditary” (HMTC; 25%) on the basis of germline RET gene mutation status and clinical phenotype 1." (PMID 25487826, 2015). "Currently, several tyrosine kinase inhibitors with anti-RET kinase activity such as vandetanib, lenvatinib, ponatinib, and carbozantinib are at various stages of clinical development for medullary thyroid carcinoma, in which RET is the critical oncogenic driver, and lung adenocarcinoma." (PMID 26078337, 2015). "However, treatment of medullary thyroid cancer with RET inhibitors has shown modest efficacy to date in clinical trials for reasons not well understood." (PMID 26065416, 2015). "In contrast, we found that RET receptor was expressed at very high levels on the membrane of MTC-TT cell line, which derives from a medullary thyroid carcinoma (MTC) associated with multiple endocrine neoplasia type 2A (MEN2A) and that produces high levels of RET mRNA copies." (PMID 23527089, 2013). "RET mutations that cause sporadic papillary thyroid cancer are rearrangements rather than point mutations like the ones found in familial medullary thyroid cancer." (PMID 24281099, 2010). "Interestingly, a similar pattern of subclonal involvement of the RET oncogene has been suggested by a study in medullary carcinoma." (PMID 16641909, 2006).
medullary thyroid carcinoma (continued). "We studied 6 medullary thyroid carcinomas and 1 C-cell hyperplasia specimen from 7 patients with MEN 2A and known RET germline mutations for allelic imbalance at the RET locus and for somatic genetic alterations at the VHL gene locus at 3p25/26 including LOH and mutations." (PMID 16707008, 2006). "Around the same time, the discovery that germline RET mutations cause multiple endocrine neoplasia type 2 (MEN2) and familial medullary thyroid carcinoma (MTC) revolutionized clinical care through genetic screening and prophylactic thyroidectomy." (PMID 41595456, 2025). "Moreover, RET fusions occur in less than 10% of non-medullary thyroid carcinoma cases." (PMID 40805132, 2025). "Frequency and the spectrum of pathogenic RET variants, risk of clinically present medullary thyroid cancer, and all-cause mortality without thyroidectomy were assessed using proportions with exact binomial 95% CIs and survival analysis adjusted for age at recruitment and sex." (PMID 40577012, 2025). "One phase 1-2 study 156 demonstrated the efficacy and safety of pralsetinib in patients with medullary thyroid cancer, with response rates of 71% in treatment-naive patients, 60% in those previously treated with cabozantinib and/or vandetanib, and 89% in patients with RET fusions." (PMID 39744583, 2025). "A preclinical study conducted in human medullary thyroid carcinoma cell lines demonstrated that adefovir dipivoxil, a drug already approved for the treatment of chronic hepatitis B, inhibited RET gene transcription, reducing the expression of endogenous RET proteins." (PMID 39199650, 2024). "Moreover, an integrated analysis of safety data of RET-Is among patients with RET fusion + NSCLC with those with medullary thyroid carcinoma and other tumors should be mandatory to define if some toxicities are only drug-dependent or can be linked also to a specific disease." (PMID 39199650, 2024). "Selpercatinib is a rearranged during transfection (RET) receptor tyrosine kinase inhibitor approved for cancers harboring RET mutations (metastatic RET fusion-positive NSCLC, advanced/metastatic RET-altered medullary thyroid cancer and papillary thyroid carcinoma)." (PMID 38202651, 2023). "Moreover, the results from this work have significant translational implications when considering that two RET kinase inhibitors, Pralsetinib and Selpercatinib, have recently been FDA-approved for non-small cell lung cancer (NSCLC) and RET+ advanced medullary thyroid cancer." (PMID 36142729, 2022). "Similarly, a single-centre study on RET gene testing revealed that more than half of patients with a Medullary Thyroid Carcinoma (MTC) and a RET pathogenic variant did not have a significant family history of cancer." (PMID 35190596, 2022). "Finally, eight of the nine individuals that received a RET pathogenic result and underwent thyroidectomy post-disclosure were diagnosed with medullary thyroid cancer (26% of participants with RET result via GSC, 89% that had thyroidectomy, median age at diagnosis 58.7 (range 33.6–72.9) years)." (PMID 35668420, 2022). "Activating gain of function mutations are specifically related to medullary thyroid carcinoma (MTC), while RET gene rearrangements have been reported in papillary thyroid carcinoma (PTC), in lung cancer, and chronic myelomonocytic leukemia." (PMID 34680178, 2021). "However, the role of CDK5 in GDNF-induced RET signaling in medullary thyroid cancer proliferation remains unknown." (PMID 34207842, 2021). "Mutations of the gene encoding the RET tyrosine kinase causes Hirschsprung’s disease (HSCR) and medullary thyroid carcinoma (MTC)." (PMID 33958373, 2021). "Furthermore, pralsetinib has also been approved for metastatic RET-mutant medullary thyroid cancer." (PMID 33504104, 2021).
medullary thyroid carcinoma (continued). "In May 2020, selpercatinib (RETEVMO, Eli Lilly Company) was approved by the FDA for metastatic RET fusion-positive non-small cell lung cancer (NSCLC) in adult patients and advanced or metastatic RET-mutant medullary thyroid cancer (MTC) in adult and pediatric (≥12 years old) patients." (PMID 34832869, 2021). "MTC has an important genetic component with about a quarter of all MTC being hereditary (familial medullary thyroid carcinoma or FMTC) and carrying a mutation in the RET protooncogene." (PMID 32244473, 2020). "Different pathogenic germline mutations in the RET oncogene are identified in MEN 2, a hereditary syndrome characterized by medullary thyroid carcinoma (MTC) and other endocrine tumors." (PMID 31288802, 2019). "Moreover, mutations in RET are also associated with the disorders such as multiple endocrine neoplasia, type IIA, multiple endocrine neoplasia, type IIB, Hirschsprung disease, and medullary thyroid carcinoma." (PMID 29954329, 2018). "In addition, although both phaeochromocytoma and medullary thyroid cancer are major features of MEN 2A and MEN 2B and somatic RET mutations are common in sporadic medullary thyroid cancer, somatic RET mutations are found in only 10% of sporadic phaeochromocytomas." (PMID 15505628, 2004). "Provided criteria for testing are fulfilled (for example, a patient presenting with medullary thyroid cancer (MTC)), insurers will often cover the cost of both germline and somatic RET testing in the USA and Europe." (PMID 40138217, 2025). "Early recognition of underlying genetic conditions has significant therapeutic and prognostic implications, especially in MEN2B, where early detection of RET-driven medullary thyroid carcinoma can be lifesaving." (PMID 41441535, 2025). "Vandetanib, an approved EGFR inhibitor for medullary thyroid cancer, targets EGFR, VEGFR, and RET, offering broad efficacy, but is limited by adverse effects like diarrhea, rash, nausea, hypertension, and QT prolongation." (PMID 40872743, 2025). "RET gene variants have been reported in a proportion of patients with familial Hirschsprung disease (F-HSCR), and certain variants are also associated with hereditary medullary thyroid carcinoma (MTC)." (PMID 40656247, 2025). "Aberrant RET signaling drives multiple malignancies including non-small cell lung cancer (NSCLC), medullary thyroid carcinoma (MTC), papillary thyroid carcinoma, pancreatic cancer, and prostate cancer." (PMID 41181595, 2025). "Vandetanib is an oral multi-TKI that inhibits RET, EGFR (Epidermal Growth Factor Receptor), and VEGFR-2/3, and is approved for the treatment of medullary thyroid carcinoma." (PMID 39199650, 2024). "Multi-gene joint analysis of RET C634R in the left nodule and BRAF V600E in the right nodule indicated a potential diagnosis of left medullary thyroid carcinoma (MTC) and right papillary thyroid carcinoma (PTC)." (PMID 40017634, 2024). "RETC634Y mutation is commonly associated with medullary thyroid carcinoma (MTC) and results in RET dimerization in the absence of its ligands, leading to the autophosphorylation of its tyrosine kinase domains." (PMID 38132167, 2023). "In September 2020, the FDA granted accelerated approval for pralsetinib to treat adult patients with metastatic fusion RET positive NSCLC, and on December 2020, for advanced or metastatic medullary thyroid cancer with genetically defective RET." (PMID 37513232, 2023). "Although NSCLC, papillary thyroid cancer (PTC), and medullary thyroid cancer (MTC) collectively account for the majority of RET-altered cancers, a plurality of additional tumor histologies also harbor RET alterations." (PMID 37627175, 2023).
medullary thyroid carcinoma (continued). "Cabozantinib has been approved in some locations for RET fusion-positive NSCLC, medullary thyroid cancer and Advanced Renal Cell Carcinoma." (PMID 36582799, 2022). "The approvals based on early phase studies regarded especially targeted therapy (anti ROS1, anti ALK, and anti-RET) in NSCLC and some rare disease (medullary and non-medullary thyroid cancer, soft tissue sarcoma, GIST)." (PMID 35205637, 2022). "Selpercatinib was authorized by the FDA and EMA in 2020 for the treatment of RET-mutant medullary thyroid carcinoma (MTC) and RAI-R TC with RET-fused." (PMID 36612173, 2022). "ARROW is a phase 1/2 study of the highly selective RET inhibitor pralsetinib in patients with medullary thyroid cancer, RET-altered NSCLC and other RET-altered solid tumors." (PMID 35962206, 2022). "The phase I/II clinical trial investigating the use of TPX‐0046 for RET‐altered NSCLC and medullary thyroid cancer is currently ongoing (NCT04161391)." (PMID 34997674, 2022). "During standard genetic diagnosis of medullary thyroid carcinoma patients (MTC), we observe the repeated appearance of one or more common polymorphisms in the gene RET; in the case of sporadic MTC, often with no additionally identified disease-causing variant." (PMID 34769224, 2021). "We first investigated the expression level of CDK5 and RET proteins in anaplastic thyroid cancer ARO, follicular thyroid cancer WRO, papillary thyroid cancer Cg3, and medullary thyroid cancer cells TT." (PMID 34207842, 2021). "Protein interaction between RET and CDK5 was further confirmed by evaluating their co-localization in human medullary thyroid cancer cells." (PMID 34207842, 2021). "Here, we investigated RET activation and its biochemically interaction with CDK5 in GDNF-induced medullary thyroid cancer proliferation." (PMID 34207842, 2021). "Cabozantinib (XL184), targeting VEGFR1/2, MET, RET, KIT and FLT3, has been assessed in several cell line models and has been approved by the FDA for the treatment of progressive medullary thyroid cancer." (PMID 31040922, 2019). "Cabozantinib, which has been approved for treating medullary thyroid cancer, is a type II inhibitor with multi-targeted tyrosine kinase for cMET, VEGFR2, AXL, KIT, TIE2, Fms-like tyrosine kinase 3 and RET." (PMID 30404198, 2018). "Vandetanib, selectively targeting RET, VEGFR, and EGFR tyrosine kinases, has been approved for the treatment of medullary thyroid carcinoma (MTC)." (PMID 28740507, 2017). "Vandetanib, which inhibits VEGF receptor dependent tumor angiogenesis and epidermal growth factor receptor (EGFR-) and RET-mediated tumor cell proliferation, along with cabozantinib, is now FDA approved for treatment of medullary thyroid cancer." (PMID 26064704, 2015). "The multikinase inhibitor vandetanib (ZD6474) is an inhibitor of RET and VEGFR1, and is approved for medullary thyroid cancer with RET fusions." (PMID 24722523, 2014). "Persistent RET activation is a frequent event in papillary thyroid carcinoma (PTC) and medullary thyroid carcinoma (MTC)." (PMID 23056499, 2012). "Similarly, retrospective studies in RET fusion-positive NSCLC and RET-mutant medullary thyroid cancer using ctDNA and tissue revealed the emergence of RET solvent-front mutations following initial responses to selpercatinib." (PMID 41228269, 2025). "Of note, selpercatinib gained prior approval on 8 May 2020 for the treatment of metastatic RET fusion-positive NSCLC in adults and advanced or metastatic RET mutant medullary thyroid cancer in patients 12 years of age or greater." (PMID 39518080, 2024). "Selpercatinib was approved for RET-mutant medullary thyroid cancers; however, no approvals currently exist for RET-mutant solid tumors." (PMID 39061168, 2024). "As for somatic RET mutation, although it has been considered a negative prognostic indicator, some argue that it does not portend compromised DSS or OS in a cohort of medullary thyroid cancer (MTC) patients." (PMID 39235852, 2024).
medullary thyroid carcinoma (continued). "Exposure of LUAD-0002AS1 (NSCLC, KIF5B–RET), ECLC5B (NSCLC, tripartite motif-containing 33 (TRIM33)–RET) and TT cells (medullary thyroid carcinoma, RETC634W) to vepafestinib resulted in efficient downregulation of RET phosphorylation at Y905 and Y1062 and downstream effectors." (PMID 37743366, 2023). "In addition to the activation of RET and STAT3, it has been noted that CDK5 regulates STAT3 in medullary thyroid cancer, influencing cell proliferation." (PMID 37046823, 2023). "Since CDK5 and RET have been reported to play an essential role in human medullary thyroid cancer cell proliferation, we next hypothesized that there might be some regulation between CDK5 and RET proteins." (PMID 34207842, 2021). "Since CDK5 has been reported to play an essential role in various types of cancer cells, including medullary thyroid cancer cells, this study aimed to investigate the role of RET-mediated CDK5 activation and their interaction in GDNF-induced human medullary thyroid cancer proliferation." (PMID 34207842, 2021). "In May 2020, the FDA approved selpercatinib for the treatment of metastatic RET-fusion positive NSCLC and metastatic RET-mutant medullary thyroid cancer." (PMID 33921237, 2021). "For example, the detection of RET M918T in cfDNA has been reported in medullary thyroid carcinoma (MTC) as a specific but not very sensitive event during follow-up." (PMID 30841521, 2019). "In a study of patients with medullary thyroid carcinoma, those treated with vandetanib (a VEGFR2 and RET inhibitor) gained body weight and muscle mass at 3 months compared with the placebo group; nevertheless, those with low muscle mass had a higher probability of DMTs." (PMID 31860408, 2019). "In our study, DOK1 tyrosine phosphorylation did not seem to be dependent on RET/PTC1, in contrast with DOK1 function in medullary thyroid carcinoma, where its phosphorylation was mediated by mutated RET." (PMID 20955590, 2010). "Since we have previously reported that CDK5 phosphorylates STAT3 at Ser727 site in prostate and medullary thyroid cancer cells, thus, we thought that STAT3 might be a potential downstream of CDK5 in GDNF-induced RET signaling in medullary thyroid cancer cell proliferation." (PMID 34207842, 2021). "This study was designed to investigate whether RET (rearranged during transfection) mRNA over-expression could be considered an alternative driver event for the development of medullary thyroid carcinoma (MTC), and if different RET isoforms could play a role in MTC tumorigenesis." (PMID 34680178, 2021). "The cancer stem cells in medullary thyroid carcinoma are characterized by chemo- and radio-resistance induced by increased signaling pathways, such as signal transducer and activator of transcription 3 (STAT3), c-Met, SOX2, rearranged during transfection (RET), CD44." (PMID 32244473, 2020). "Finally, our findings indicate that pharmacological inhibition of the RET pathway in severe pathologies, such as medullary thyroid cancer, should not be confronted with undesirable T cell production failure." (PMID 23300832, 2012). "A total of 48 patients with sporadic medullary thyroid carcinoma (MTC) with no tumours, signs, or symptoms which may be attributed to MEN syndromes; with no family history of MTC or MEN2 syndrome; and with negative RET pathogenic variant status in genetic diagnostics were included in the study." (PMID 34769224, 2021). "However, there is a lack of consensus on whether individuals with F-HSCR and RET mutations should undergo surveillance for medullary thyroid carcinoma (MTC; OMIM#155240) or PHEO, particularly when MTC is absent." (PMID 40656247, 2025). "The RTK inhibitor vandetanib specifically inhibits the activity of RET, EGFR and VEGFR-2 and -3 and is already approved in the European Union for the treatment of advanced, non-resectable medullary thyroid carcinoma (MTC), another rare subtype of TC1,2,9." (PMID 40940449, 2025).